PCDH17 (protocadherin 17)
Diseases named in the same sentence as PCDH17 in open-access papers (continued):
Sharing a sentence is not in itself a finding about the gene and the disease.
tumor (36 papers, 2012 to 2025). "We primarily aggregated genes from inflammatory signaling pathways in tumor-associated endothelial cells, with a focus on PCDH17, to delineate the differentiation trajectories within these cells." (PMID 40487760, 2025). "A thorough examination was carried out to explore the presence of PCDH17 in cancerous tumor tissues and its association with genes related to inflammation." (PMID 40487760, 2025). "Tumor mutational loads of potential therapeutic drug target genes exhibited variations in both PCDH17 groups." (PMID 40487760, 2025). "PCDH17 (protocadherin 17) is a cell–cell adhesion tumor suppressor protein, whose loss can co-occur with tumor progression by enhancing proliferation and EMT." (PMID 35406495, 2022). "Silencing of PCDH17 expression through hypermethylation of the promoter or other mechanisms leads to loss of its tumour-suppressive activity." (PMID 33369468, 2020). "As distinct from the tumor suppressive signatures that were positively associated with PCDH17 expression, those negatively correlated with PCDH17 expression consists mainly of oncogenes." (PMID 30922328, 2019). "Methylation could occur in PCDH8, PCDH10, and PCDH17 in both PC tumor tissue and serum, and is associated with poor prognosis and shorter biochemical relapse-free survival." (PMID 33369468, 2020). "PCDH17 is a member of the protocadherin superfamily that acts as a methylated gene and regulates apoptosis, autophagy, and drug resistance in tumor cells." (PMID 39837826, 2025). "Subsequently, the relationship between PCDH17 and immunotherapeutic target genes exhibited variability across different tumor types." (PMID 40487760, 2025). "Although some studies have indicated that PCDH17 exhibits a phenomenon of inhibiting tumor progression." (PMID 39837826, 2025). "Single-cell sequencing results proved that PCDH17 was highly expressed in the endothelial cells of the left ventricle of the mouse heart, providing support for the use of PCDH17 as a novel marker of the tumor endothelium." (PMID 39837826, 2025). "PCDH17 expression exhibited a decline within the tumor, resulting in a decrease in the abundance of T-cell infiltration." (PMID 40487760, 2025). "Our results demonstrate reduced metastasis of tumor cells to the liver and lungs in PCDH17–/– mice, potentially due to reduced VEGFR2 signaling." (PMID 39837826, 2025). "As a result, PCDH17 regulates the inflammatory response in the tumor microenvironment by inhibiting it through endothelial cells." (PMID 40487760, 2025). "Gen1LMD uniquely upregulated FAM83F, a WNT signaling regulator, and downregulated tumor suppressor PCDH17, which inhibits WNT signaling and metastasis." (PMID 39416100, 2025). "PCDH17 was found to play a critical role in regulating immune events essential for tumor growth control." (PMID 40487760, 2025). "This study reveals PCDH17 as a context-dependent regulator of tumor microenvironments across cancers." (PMID 40487760, 2025). "Next, we will explore how the expression of PCDH17 in endothelial cells influence the tumor metastasis." (PMID 39837826, 2025). "PCDH17 has the potential to be a marker for predicting tumor metastasis as well as a viable treatment target for CRC." (PMID 39837826, 2025). "The protein expression of PCDH17 is significantly correlated with the tumor staging and lymph node metastasis in CRC." (PMID 39184862, 2024). "The authors suggest the possibility to consider recurrent PCDH17 hypermethylation as a diagnostic and prognostic biomarker in LSCC, even if further studies enrolling more patients with different tumor grades and stages are needed." (PMID 35406495, 2022).
tumor (continued). "In a previous study, we demonstrated that lower protein expression of PCDH17 was significantly correlated with low T stage, decreased lymph node metastasis, and low tumor stage in CRC patients compared with paired surgical margin tissues." (PMID 31815010, 2019). "The gene locates on chromosome 13q21, a region for which homozygous deletion often occurred in cancers; this suggests PCDH17 as a potential tumor suppressor beyond its role in neural development." (PMID 30922328, 2019). "In accordance with the in vitro results, the tumor size of the 5-FU plus 3-MA group was significantly larger than that of the 5-FU group (p < 0.01), indicating that PCDH17 can induce prodeath autophagy in vivo when CRC cells are treated with 5-FU." (PMID 31815010, 2019). "PCDH17 has been shown to have suppressive effects on the proliferation of tumor cells by inducing apoptosis and cell cycle arrest." (PMID 27351130, 2016). "Vector-transfected cells showed spindle-shaped morphology like fibroblasts, while a large proportion of PCDH17-transfected cells are elliptical shaped, suggesting that PCDH17 most likely reversed tumor cell EMT." (PMID 27351130, 2016). "Reduced expression of active β-catenin and its downstream target genes c-Myc and cyclin D1 was also observed in PCDH17-transfected tumor cells (MB468, MCF7 and MB231) by western blot." (PMID 27351130, 2016). "In GC therapy, the induction of autophagy by anti-cancer drugs, such as protocadherin 17 and vincristine, has been shown to either suppress or promote tumor cell growth." (PMID 28070138, 2016). "This signaling pathway most likely also contributes to the tumor-suppressive effect of PCDH17, as c-Myc is an important oncogenic transcriptional factor." (PMID 27351130, 2016). "Moreover, single-cell RNA sequencing data analysis further revealed that PCDH17 was more specifically higher expressed in tumor endothelium than FAM167B." (PMID 39837826, 2025). "According to The Genotype-Tissue Expression (GTEx) project, PCDH17 is highly and specifically expressed in Lung tissue and therefore may simply represent the stroma in which the tumor cells reside." (PMID 40813609, 2025). "PCDH17 is involved in proliferation, apoptosis, and drug resistance in tumor cells." (PMID 39837826, 2025). "Additionally, a tumor transendothelial migration assay demonstrated that PCDH17 facilitates the extravasation and metastasis of HCT116 cells (P < 0.001)." (PMID 39837826, 2025). "Furthermore, PCDH17 KO mice had significantly reduced liver and lung metastases of tumor cells compared to wild-type mice." (PMID 39837826, 2025). "Furthermore, the tumor transendothelial migration assay also demonstrated that PCDH17 facilitates the extravasation and metastasis of HCT116 cells was abolished in HUVECs treated with siVEGFR2 (P < 0.001)." (PMID 39837826, 2025). "In contrast,EC5 and EC6 subclasses exhibited conserved pro-angiogenic signatures encompassing established vascular morphogenesis regulators (CD34,AQP1) and emerging angiocrine signaling components (RAMP2/3,CRIP2,PCDH17),consistent with previous reports on tumor neovascularization dynamics." (PMID 41394809, 2025). "Conversely, the livers and lungs of PCDH17 KO mouse displayed lower tumor foci." (PMID 39837826, 2025). "The presence of PCDH17 in endothelial cells was verified through various immunofluorescence techniques, and a simultaneous decline in its levels was observed alongside the decrease in inflammatory factors within the tumor microenvironment." (PMID 40487760, 2025). "The differential effects of PCDH17 on tumor cells and endothelial cells might be attributed to the specific tissue structure and function of endothelial cells." (PMID 39837826, 2025). "PCDH17 exhibited differential expression across various tumor types." (PMID 40487760, 2025). "PCDH17 has been recently defined as a new methylation driver gene that plays a critical role in the initiation, promotion and progression of different human tumours." (PMID 35409379, 2022).
tumor (continued). "PCDH8 and PCDH17, in contrast, may have multiple tumor suppression functions, such as involvement in cell-cell adhesion, signal transduction, and growth control, although the exact function of both the PCDHs is poorly understood." (PMID 33369468, 2020). "Despite progress in understanding its tumor-suppressive functions and clinical relevance in solid tumors, the role of PCDH17 in hematological malignancies remains largely unknown." (PMID 30922328, 2019). "The effect of PCDH17 on tumor cell growth was also assessed by immunohistochemical staining." (PMID 27351130, 2016). "The PCDH17 gene, located in the region of the SNP on SSC 11, belongs to the protocadherin gene family and its methylation level has been suggested to be important for tumour progression in several cancers and is shown to be associated with body weight and growth." (PMID 40266940, 2025). "Considering that PCDH17 is a known tumor suppressor but not previously associated with lung carcinogenesis, we performed experimental investigation of its functional role in this tumor type." (PMID 33859751, 2021). "We next investigated whether tumor cell growth was inhibited by ectopic PCDH17 expression." (PMID 31815010, 2019). "The protein encoded by PCDH17 may play a role in the establishment and function of specific cell-cell connections in the brain, but its role in tumor tissue is not clear." (PMID 22363777, 2012). "Among them, PCDH17 and FAM167B were specifically expressed in the tumor endothelial cells than other genes." (PMID 39837826, 2025). "Second, we demonstrated that PCDH17 disrupts endothelial cell adhesion junctions, increases permeability, and facilitates the intravasation of CRC tumor cells." (PMID 39837826, 2025). "The proteins protocadherin 17 (A0A8I3PDN1) and albumin (A0A8I3MY51) were the most abundant in both groups composed of animals with neoplasms (GI and GII)." (PMID 39057100, 2024). "Noteworthy is the impact of PCDH17 expression on the TNM staging of GC, thus rendering it a promising candidate as a putative tumor marker." (PMID 39184862, 2024). "Compared to primary tumours, CSF cfDNA more frequently lost 13q regions containing PCDH9 and PCDH17 (members of the cadherin superfamily) and KLHL1, an actin binding protein with a role in cytoskeleton reorganisation." (PMID 37973922, 2023). "Among them, we identified and experimentally confirmed a group of methylation driver genes (e.g., PCDH17, IRX1, TBX5 and HSPB6) that play a critical role in neoplasia initiation, promotion, and progression." (PMID 33859751, 2021). "Our previous study showed that the protocadherin 17 (PCDH17) gene was frequently methylated and functioned as a tumor suppressor in CRC." (PMID 31815010, 2019). "PCDH10, PCDH17 and PCDH20 expression levels were downregulated in this neoplasm." (PMID 33369468, 2020). "Although reduced PCDH17 expression has been reported in a number of tumor types, it has, thus far, not been demonstrated in the context of AML." (PMID 30922328, 2019). "However, there is no mechanistic data on the role of PCDH17 in modulating the tumor vascular endothelial barrier and promoting distant metastasis of CRC." (PMID 39837826, 2025). "In addition, according to a study, PCDHs located on chromosome 13q21, such as PCDH8, PCDH9, PCDH17, and PCDH20, may be involved in tumor suppression." (PMID 33369468, 2020). "While previous studies have indicated that PCDH17 is commonly methylated and acts as a suppressor of tumors in CRC, the precise role and mechanism of PCDH17 in tumor vascular endothelial cells has not been elucidated." (PMID 39837826, 2025).
cancer (23 papers, 2012 to 2025). A tumor composed of atypical neoplastic, often pleomorphic cells that invade other tissues. "The frequency of PCDH8 and PCDH17 methylation is high in this cancer, and the PCDHs are associated with malignancy clinicopathological characteristics and unfavorable prognosis." (PMID 33369468, 2020). "In line with this, PCDH17 gene is found transcriptionally silenced in various human cancers, due to mechanisms including deletion, mutation, and more often, promoter methylation." (PMID 30922328, 2019). "We also validated the LC substrate candidates CLMP, ICAM1, PCDH17, as well as the cancer-related GPNMB and TIMD4 as substrates." (PMID 40593564, 2025). "Protocadherin 17 (PCDH17), which belongs to the protocadherin gene family, has been evidenced to be linked with the activation of autophagy in cancer cells." (PMID 38390204, 2024). "Like other PCDHs, PCDH17 is a tumor suppressor gene and its promoter shows hypermethylation in different cancers (e.g., breast, prostate)." (PMID 36698136, 2023). "The high-expression group of PCDH17 demonstrated significantly elevated scores in immune-related processes, including cancer antigen presentation, T cell recruitment, CD8-positive T cell recruitment, and Treg cell recruitment, compared to the low-expression group." (PMID 40487760, 2025). "This research has important implications for targeting PCDH17 in cancer treatment." (PMID 39837826, 2025). "Some reports showed that PCDHs are dysregulated in various cancers, such as PCDH10, PCDH17 and PCDH8." (PMID 39123216, 2024). "The results showed that PCDH17 and BECN1 were highly expressed in the cytoplasm of cancer cells, and their expression was significantly correlated (p < 0.05)." (PMID 31815010, 2019). "Methylation levels of two genes, PCDH17 and TCF21, were quantified in a total of 12 cancer cell lines and 318 clinical samples." (PMID 27594736, 2016). "Among the cancer driver genes that experienced epigenetic changes in at least five cancer types, we identified eight genes: CEP55, PIF1, RRM2, NCAPH, ZEB2, CIT, FLI1, and PCDH17." (PMID 31900418, 2020). "MAL and PCDH17 CpG-rich regions have never been functionally characterised in humans or canines, and, to the best of the authors’ knowledge, the only available data concern the localisation and methylation profile of specific CpGIs in human cancers." (PMID 35409379, 2022).
heart disease (2 papers, 2020 to 2025). "The lncRNA DCM-related factor (DCRF) is associated with the development of DCM and regulates autophagy by acting as the ceRNA of miR-551b-5p; here, DCFR binds to miR-551b-5p to upregulate protocadherin-17 (PCDH17) that increases autophagy and has been reported to aggravate heart diseases." (PMID 40823532, 2025).
PCDH17 also shares sentences with these, for which no sentence is quoted: prostate carcinoma (4 papers); nasopharyngeal carcinoma (3); colorectal (2); Anxiety (1); autism (1); cholangiocarcinoma (1); colon adenoma (1); depression (1); esophageal neoplasms (1); gastric cancer (1); Hematuria (1); hypertrophy (1); kidney cancer (1); laryngeal squamous cell carcinoma (1); lymph node metastasis (1); metastatic cancer (1); microcephaly (1); Myocardial fibrosis (1); neuroblastoma (1); Neurodevelopmental delay (1); neurodevelopmental disorder (1); prostate (1); renal clear cell carcinoma (1); squamous cell lung carcinoma (1); urothelial cell carcinoma (1).